CDKN1A (cyclin dependent kinase inhibitor 1A)
Diseases named in the same sentence as CDKN1A in open-access papers (continued):
Sharing a sentence is not in itself a finding about the gene and the disease.
breast carcinoma (continued). "Combinatorial exposures inhibited breast cancer cell growth and induced death, followed by RARB hypomethylation and numerous increases in RARB, PTEN, and CDKN1A transcript levels." (PMID 35327559, 2022). "UCA1 also recruits EZH2 to the promoter of CDKN1A/p21 gene to suppress its expression and activate the PI3K/Akt pathway, thereby contributing to tamoxifen resistance in breast cancers." (PMID 36010595, 2022). "For example, the abundance of the transcript for Cdkn1a, the cyclin dependent kinase inhibitor, is increased in PND4 cKO mice in the present study, consistent with its regulation by NR5A2 in breast cancer cells." (PMID 33441767, 2021). "Using representative breast cancer cell lines, we also demonstrated elevated expression of miR-17 and miR-19a in BL1, coincident with suppressed expression of CDKN1A, FAM214A, and INPP4B, validating the patient-derived association." (PMID 32085745, 2020). "The combinatorial exposures synergistically or additively inhibited the growth and induced apoptosis of breast cancer cells, followed by RARB hypomethylation with concomitant multiple increase in RARB, PTEN, and CDKN1A transcript levels." (PMID 30544666, 2018). "We validated by real-time qPCR the increased expression of CDKN1A and CDKN1B in PC and breast cancer cells." (PMID 29381681, 2018). "Inhibition of AKT had only modest effect on CDKN1A phosphorylation in endothelial cells and a partial inhibition of AKT was reported earlier in breast carcinoma cells by C12-HSL." (PMID 29854771, 2018). "A glimpse into the mechanistic function of LSD1 on the chromatin structure comes from studies in breast cancer cells demonstrating that LSD1 is involved in 1,25-D3-mediated chromatin looping on the CDKN1A promoter." (PMID 28811844, 2017). "STAT6 was found to be a novel target of PVT1-derived miR-1207-5p, and miR-1207-5p promoted breast cancer cell growth by targeting STAT6, which in turn control CDKN1A and CDKN1B, confirming the tumor suppressing role of STAT6 in breast cancer." (PMID 28422733, 2017). "It has previously been shown that Cdkn1a expression is elevated on inactivation of endogenous Tbx2 in the murine B16 melanoma and the human MCF-7 breast cancer cell line." (PMID 23341776, 2013). "FOXO3A, another member of the forkhead box O family of transcription factors is also regulated by miR-96 expression in breast cancer, which results in subsequent downregulation of CDKN1B and CDKN1A." (PMID 24260486, 2013). "Previously, we have shown that Id1/3-PA7 regulates the expression of CDKN1A and CDKN1B in a dose-dependent manner in breast cancer cells MCF-7 and MDA-MB-231, which contain the homozygous deletions of the gene CDKN2A." (PMID 20842131, 2010). "We identified and validated TMEM41B as a target of miR-660-5p in breast cancer cells, which aligns with previous findings that miR-660-5p promotes breast cancer progression by targeting TET2 and activating the PI3K/AKT/mTOR pathway and the miR-660-5p/TFCP2/CDKN1A pathway." (PMID 39709500, 2024). "In addition to CDKN1A, HEB and E2A co-occupy three TSG loci, APC, a haplo-insufficient tumor suppressor, ZMYND11 a chromatin reader and tumor suppressor in breast cancer and CUX1, a homeodomain transcription regulator and haploinsufficient tumor suppressor." (PMID 35401501, 2022).
breast carcinoma (continued). "However, we find that ETV4 downregulates CDKN1A in prostate cells and also in MCF7 breast cancer cell line." (PMID 32791988, 2020). "Our studies indicated that chemotherapy-driven increases in the CDKN1A/PTN/PTPRZ1 axis play a critical role in chemoresistance, which suggests a novel strategy to enhance chemosensitivity in breast cancer cells, especially in those of the triple-negative subtype." (PMID 30497491, 2018). "In breast cancer, the H3K36me2 demethylase activity is essential for CCNA1 transcription and cell proliferation, by contrast, in HCC, our data revealed that the enzyme activity is seemingly unnecessary for CDKN1A activation and cell proliferation." (PMID 26760772, 2016). "Similarly, in MCF7 human breast cancer cells and in RWPE-1 cells ChIP-qPCR suggested VDR binding to the CDKN1A locus TSS, and to sites 2.2 and 4.7 kb upstream of it." (PMID 24202443, 2013). "This set comprised senescence markers (CDKN1A, LMNB1, MKI67), apoptosis regulators (BCL2, BCL2L1), a highly overexpressed gene (ITGB6), and drug targets (ACTA2, GSDMC, KRT6A, PDE1A, PSMA8), all of which showed strong concordance with our RNA-seq data in all four breast cancer cell lines." (PMID 40312750, 2025). "In addition, both normal vascular smooth muscle cells of mouse and non-neoplastic human breast cancer cells were induced to partial arrest in G2/M 1A (CDKN1A) under simulated microgravity." (PMID 38928190, 2024). "Besides breast cancer cells, blockage of c-Myc and TGF-β pathways in Smyca-overexpressing HCC cell line NTU-BL also showed contrasting effects on cell proliferation and the expression of cell cycle regulators CDKN1A and CCNA1 (also known as cyclin A1)." (PMID 35794621, 2022). "Alongside with the established senescence markers like CDKN1A and LMNB1, our transcriptome analysis identified a distinctive expression pattern, comprising genes upregulated across all cell lines exclusively during TIS, which may serve as a specific TIS signature in breast cancer." (PMID 40312750, 2025). "Intriguingly, METTL3 depletion has also been found to activate the CDKN1A/EMT pathway and m6A-BAX/caspase-9/-3/-8 cascade, thereby promoting proliferation, migration, and drug resistance in hormone receptor-positive HER2-negative breast cancer (HR+HER2-BC)." (PMID 40406121, 2025). "This indicates that CDKN1A and MINK1 are downregulated in breast cancer relative to normal tissue, while SQSTM1 shows upregulation in the same comparison." (PMID 39963142, 2025). "Five genes (MMP3, CDKN1A, RUNX1, TIMP2, CCND1) are common in cervical, ovarian, endometrial cancers, but not in breast cancer." (PMID 31205821, 2019).
prostate carcinoma (96 papers, 2006 to 2025). A carcinoma that arises from epithelial cells of the prostate gland. "In one study, advanced prostate cancer patients had a higher frequency of a variant on the 3’UTR of CDKN1A and the gene has received attention as a potential therapeutic target for prostate cancer." (PMID 39132489, 2024). "Of note, data on the prognostic relevance of CDKN1A expression showed that increased expression of CDKN1A were associated with poor prognosis in esophageal, ovarian, prostate cancers, and gliomas." (PMID 35186763, 2022). "Increased CDKN1A levels are associated with poor outcome in esophageal, ovarian, prostate cancers as well as in gliomas, while loss of CDKN1A expression is associated with decreased survival in breast, cervical, gastric, and ovarian cancers." (PMID 32079343, 2020). "The CDKN1A genotypes CT and TT are associated with an increased risk of advanced prostate carcinoma compared with the CC genotype." (PMID 28651018, 2017). "CDKN1A has been shown to be associated with colorectal and prostate cancer risk." (PMID 25475428, 2014). "For the G2 radiosensitive prostate cancer donors, 60% (3/5) CDKN1A, 40% FDXR, 80% SESN1 and 40% PCNA gene expression exceeded the fold change threshold." (PMID 34638945, 2021). "Specifically, half of the “prostate cancer” pathway DEGsSD had previously been referred to in the literature (AR, CDKN1A, CTNNB1, EGFR, KLK2, NKX3-1, PDGFRA, SRD5A2)." (PMID 34768937, 2021). "In summary, the current study provides evidence showing that the druggable NR HNF4α performs a tumor suppressor function in prostate cancer, by suppressing cellular senescence via its transactivation of CDKN1A." (PMID 31695151, 2020). "We also characterized that the HNF4α-induced inhibition of cell proliferation and cell-cycle arrest in prostate cancer cells was mediated by a mechanism of its direct transactivation of CDKN1A (p21WAF1/CIP1) gene." (PMID 31695151, 2020). "For instance, the suppressing cell growth and promoting cell cycle arrest functions of CDKN1A were observed in gastric cancer and prostate cancer." (PMID 30497491, 2018). "CDKN1A encodes protein p21, which plays an important role in KEGG prostate cancer pathway and is again verified by the Androgen Responsive Gene Database." (PMID 30598101, 2018). "With publicly available data sets, we found expression profiling of high Embigin (gene name: EMB) or low p21WAF1 (gene name: CDKN1A) mRNA in prostate cancer patients, which leads to worse overall survival." (PMID 30041429, 2018). "Consistently, in several solid tumors (such as prostate cancer, ovarian cancer and lung cancer), CDKN1A/p21 and CDKN1B/p27 were identified as EZH2 targets by ChIP-qPCR analysis, and inhibited due to elevated level of EZH2." (PMID 27998273, 2016). "The up-regulation of CDKN1A mRNA is also consistent with AR-mediated transcriptional activation, which has been reported previously in prostate cancer-derived cell lines." (PMID 26372468, 2015).
prostate carcinoma (continued). "In addition, the Apc-Cdkn1a network also suggests that certain interactions previously associated with other cancer models – such as the SRC-CCND1 functional association found in prostate cancer, or the phosphorylation of CDK4 by SRC in a cell line – are relevant in this model of colon cancer." (PMID 20824133, 2010). "PI3K/AKT signaling has been demonstrated to increase CDKN1A expression in prostate cancer." (PMID 38256084, 2024). "Furthermore, half of the “prostate cancer” pathway DEGsSD are well described in the PCa literature (AR, CDKN1A, CTNNB1, EGFR, KLK2, NKX3-1, PDGFRA, SRD5A2), confirming that this is a pivotal pathway to specifically target clinical questions on canine PCa." (PMID 34768937, 2021). "Therefore, comprehensive experimental investigations revealed that ginsenoside Rh2 inhibits prostate cancer cell growth by inhibiting miRNA-4295, which activates CDKN1A." (PMID 33680956, 2020). "The four genes CDH1, MYC, SOS2, and CDKN1A are obtained from the prostate cancer network." (PMID 29670664, 2018). "Recently, we have demonstrated that TLX, which is upregulated in prostate cancer, can promote its initiation and progression by repression of oncogene-induced senescence via its differential co-regulation of senescence-regulatory genes CDKN1A and SIRT1." (PMID 29555975, 2018). "The pattern was high EMB and low CDKN1A mRNA expression in prostate cancer tissues." (PMID 30041429, 2018). "In contrast, androgen-repressed genes that inhibit prostate cancer proliferation, such as CCNG2 and CDKN1A, were induced by LLS30." (PMID 39941722, 2025). "(2006) successfully developed saRNAs targeting CDH1, CDKN1A, and VEGF in prostate cancer cell lines." (PMID 36700046, 2022). "Of the 32 target hub genes, 4 were mapped to cell signalling pathways including ACVR1 and ACVR2B in TGF-beta signalling, CDKN1A and GSK3B in ErbB signalling (adj.P val = 0.016) and CDKN1A and GSK3B genes in Prostate cancer pathways (adj." (PMID 36468011, 2022). "Donor samples deemed to be G2 chromosomal radiosensitive (152 abs/100 meta) were our focus, because although CDKN1A, FDXR and SESN1 were clearly radiation-responsive genes, this was consistently observed in both healthy control and prostate cancer donors." (PMID 34638945, 2021). "Surprisingly, in prostate cancer, LSD1 knockdown resulted in increased H3K4me2 in the CDKN1A promotor, but repressed CDKN1A transcription." (PMID 31514410, 2019). "Liquid biopsy of exosomes isolated from patients with prostate cancer revealed that exosomes are enriched for genes that are hallmarks of prostate cancer, such as androgen receptor, kallikreins (KLK2), cyclin-dependent kinase inhibitor 1A (CDKN1A), KLK10, JUN, and B2M (β2 microglobulin)." (PMID 36726968, 2022). "Another study showed that ginsenoside Rh2 inhibited the proliferation of prostate cancer cells in a dose-dependent manner, and no CDKN1A cell cycle inhibitor was observed in the increased protein of ginsenoside Rh2." (PMID 33680956, 2020).
prostate carcinoma (continued). "Finally, the “prostate cancer” pathway also includes DEGsSD that are relatively specific to the (human) prostate (SRD5A2, KLK2, NKX3-1 and CREB3L4), proto-oncogenes (EGFR, PDGFRA, PDGFRB, NRAS) and druggable candidates (PIK3CD, CTNNB1, PIK3CG, CDKN1A)." (PMID 34768937, 2021). "The “prostate cancer” pathway also comprises genes that are relatively specific to the (human) prostate (CREB3L4, KLK2, NKX3-1 and SRD5A2), proto-oncogenes (EGFR, NRAS, PDGFRA and PDGFRB), and druggable candidates (CDKN1A, CTNNB1, EGFR, NRAS, PDGFRA, PDGFRB, PIK3CD and PIK3CG)." (PMID 34768937, 2021). "Several genes have been identified as epigenetic targets of RNF2; for example, cyclin-dependent kinase inhibitors 1A and 2A (CDKN1A and CDKN2A) were shown to be RNF2 targets in hepatic stem/progenitor cells, and thioredoxin interacting protein was reported to be an RNF2 target in prostate cancer." (PMID 33346749, 2020). "FOXP3 has been shown to exert its growth inhibitory effect on breast and prostate cancer cells by transcriptionally repressing the expression of specific oncogenes (HER2, SKP2, SATB1 and MYC), and inducing the expression of specific tumor suppressor genes (CDKN1A, LATS2)." (PMID 24406338, 2014). "Interestingly, CDKN1A and BAX were upregulated by TSPX-overexpression in LNCaP cells, but not in TSPX-high clinical prostate cancer samples." (PMID 30863497, 2019).
melanoma (85 papers, 2004 to 2025). A malignant, usually aggressive tumor composed of atypical, neoplastic melanocytes. "Sirt1 stable silencing increased Mxd1 mRNA expression and led to down-regulation of MYC targets, such as Cdkn1a, Bcl2 and Psen2, whose upregulation is associated with human melanoma aggressiveness and poor prognosis." (PMID 29383100, 2017). "CDKN1A has been previously implicated as an EZH2 target gene in melanoma and other cancers and can promote G2/M arrest." (PMID 26304929, 2015). "The increased expression of EZH2 in melanoma results in the hyper-activation of PRC2 with consequent tri-methylation of H3K27, silencing of CDKN2A and CDKN1A tumor suppressor genes, and is associated with thicker primary melanomas, aggressive metastatic behavior, and a poor prognosis." (PMID 31861757, 2019). "Almost all studies about CDKN1A and melanoma suggest that the up-regulation of CDKN1A expression can inhibit the growth of melanoma cells, accelerate aging, and improve the sensitivity of therapeutic drugs." (PMID 38070141, 2023). "Meanwhile, CDKN2A, CXCR4 and RAD51 were significantly up-regulated in melanoma compared with normal skin except CDKN1A (significantly down-regulated)." (PMID 38070141, 2023). "Compared to the control, an increase in the CDKN1A mRNA expression was detected in both melanoma cell lines treated with PTB for 12 h." (PMID 36674631, 2023). "Immunohistochemical analysis showed that compared with normal tissues, the protein level of CDKN1A was significantly down-regulated in melanoma, while the CDKN2A protein level was significantly up-regulated." (PMID 38070141, 2023). "Deregulated CDKN1A expression was associated with cisplatin resistance in non-small cell lung cancer (NSCLC), and with paclitaxel resistance in melanoma." (PMID 36768681, 2023). "In melanoma patients, CDKN1A (14%) and CDKN2A (34%) had a very high frequency of genetic aberration (inframe mutation, missense mutation, truncating mutation, amplification, deep deletion, mRNA high, mRNA low, protein high and low)." (PMID 38070141, 2023). "In melanoma cells, disturbances in CDKN1A expression are frequent, and usually lead to their uncontrolled proliferation." (PMID 36674631, 2023). "In melanoma, miR-363-3p was indicated in the targeting of the inhibitor of cell cycle progression of cyclin-dependent kinase inhibitor 1A (CDKN1A)." (PMID 32645881, 2020). "The hydroxymethylation enzyme, Tet2, was revealed to stimulate expression of the cell-cycle inhibitors,cyclin-dependent kinase inhibitor 1A (CDKN1A) andCDKN1B, resulting in dormancy of the melanoma cells." (PMID 31624492, 2019).